KRAS (KRas proto-oncogene, GTPase)
Diseases named in the same sentence as KRAS in open-access papers (continued):
Sharing a sentence is not in itself a finding about the gene and the disease.
cancer (continued). "Activating KRAS mutations occur frequently in cancers and are usually drivers of tumor initiation and cancer progression." (PMID 30223576, 2018). "Although frequently observed in cancer, not only is the basis for the specific frequencies of KRAS G12X mutations poorly understood, but also the effects of these specific mutations on a molecular scale are not clear." (PMID 30199525, 2018). "KRAS mutated cancer cells were recently shown to rely on GOT1 to support long-term cell proliferation." (PMID 29751795, 2018). "There were 21 variants that had allele frequencies > 0.02 in the sample of 621 cancer patients, 17 of which were common germline SNPs and 4 of which were common somatic driver mutations (2 in KRAS and 2 in PIK3CA)." (PMID 29721196, 2018). "We sought to use the CRISPR/Cas9 system to introduce indel mutations into the genomes of cancer cells specifically at the KRAS mutated codon-12 sites." (PMID 30089886, 2018). "We predicted that cancer lines with mutations in KRAS or EGFR would be more sensitive to the potential effects of BCI treatment on numbers of viable cells, since DUSP6 would be required to restrain the toxic effects of P-ERK in these cells." (PMID 30475204, 2018). "For this reason, KRAS mutation testing has become increasingly common in clinical practice for personalized cancer treatments of CRC patients." (PMID 29304017, 2018). "These authors also detected KRAS mutations significantly more often in IAR undergoing cancer screening than in controls." (PMID 30241369, 2018). "The present study demonstrated a novel method for inhibiting the growth of cancer cell lines with oncogenic KRAS by targeting the mutated gene using CRISPR/Cas9." (PMID 30089886, 2018). "Recently, in PDT, several photosensitisers targeting key molecules such as KRAS and Ki-67, which are associated with aggressive cancer cells, have been explored." (PMID 29891945, 2018). "KRAS isoform specific mutation frequency likewise varies with cancer type, as do downstream signaling processes." (PMID 29851957, 2018). "KRAS is the most common and, simultaneously, the most ambiguous oncogene implicated in human cancer." (PMID 29464099, 2018). "The proto-oncogene KRAS performs an essential function in normal tissue signaling, and the mutation of KRAS gene is a key step in the development of many cancers." (PMID 30012129, 2018). "Therapeutic approaches for treating cancers with such mutations have focused on targeting the downstream protein effectors of KRAS." (PMID 30089886, 2018). "We validated this homogeneous process by evaluating the effects ofwell-characterized anticancer agents against four patient-derived pancreaticcancer KRAS mutant-associated primary cells, including cancer-associatedfibroblasts." (PMID 29673279, 2018). "Each microdissected sample was also tested for cancer hotspot mutations on KRAS, BRAF and NRAS genes, and for the T790M EGFR resistanc e mutation, but no mutation was found." (PMID 29492209, 2018). "On the other hand, the high sensitive KRas-mutated cancer cells show lower Ras-GTP level and signal output after Spiclomazine treatments." (PMID 29467941, 2018). "The mutated forms of KRAS-4B not only activate their downstream signaling cascades, but also interact with each other and subsequently promote the proliferation of cancer cells and induce resistance to standard cancer therapies." (PMID 29843637, 2018). "Mutations in KRAS are frequent in human cancer, yet effective targeted therapeutics for these cancers are still lacking." (PMID 30482246, 2018). "Ribociclib also shows anti-tumor activity in pRB-positive cancers driven by activated oncogenes that are located upstream, such as activating mutations of KRAS and inactivation of PTEN11." (PMID 29789630, 2018). "In Non-Small Cell Lung Cancer (NSCLC), the main lung cancer subtype that accounts for the highest number of cancer-related deaths, KRAS is mutated in 30% of the cases." (PMID 29721157, 2018).
cancer (continued). "Cultured cancer cells harboring mutations in KRAS and BRAF were shown to take up DHA via GLUT1 when incubated with mM concentrations of ascorbate, and this was associated with a loss of cell viability." (PMID 30018566, 2018). "The results of the MTT cell viability assays validated the use of specific sgRNAs to inhibit the proliferation of cancer cells by selectively targeting oncogenic mutations of KRAS codon-12." (PMID 30089886, 2018). "KRAS mutations are common in various types of cancer, and it has been studied as a drug target for many years." (PMID 29844447, 2018). "Although activating mutations in codons 12 and 13 of KRAS are the most commonly occurring isoforms in human cancers, variants were limited to codon 12 in the present cohort." (PMID 29973234, 2018). "It has been reported that activating mutations of KRAS-4B, within the mutated Ras family, occurs in approximately 21% of all human cancers, and accounts for approximately 90% of pancreatic cancers, 45% of colon cancers, and 30% of lung cancers, respectively." (PMID 29843637, 2018). "Here we investigate the biomarkers of activity of the clinical BET inhibitor GSK525762 (I-BET; I-BET762) across cancer cell lines and demonstrate that KRAS mutations are novel resistance biomarkers." (PMID 29674704, 2018). "RAS and its downstream effectors have been targeted to develop therapeutic inhibitors in various cancers with frequently mutated KRAS or BRAF54–56." (PMID 29915291, 2018). "In a noteworthy example, while KRAS-mutant cancers exhibit resistance to low-glucose growth conditions, glucose deprivation has been shown to drive the accumulation of novel KRAS mutations in KRAS wild-type cancers." (PMID 29459886, 2018). "The overlap was 15 of the up-regulated and 2 of the down-regulated genes, suggesting that YAP1 S127 and KRAS G12V up-regulated mitosis and cell cycle-associated genes whose high expression is associated with poor survival pan-cancer." (PMID 30353028, 2018). "KRAS mutations located in codon 12 and codon 13 of exon 26 are among the most frequently detected activating mutations in human cancers, being present in 65% to 100% of pancreatic cancer and 30% to 50% of colorectal cancer cases." (PMID 30504843, 2018). "In Pancreatic Ductal Adenocarcinoma (PDAC), which presents the lowest survival rates among all cancers, 90% of the tumors harbor KRAS mutations." (PMID 29721157, 2018). "Perhaps related, PIP5K1A was also not identified in whole-genome CRISPR-Cas9 loss-of-function screens of KRAS-mutant cancer cell lines (e.g., ref.59)." (PMID 30194290, 2018). "Evidence shows that cancer cells with a KRAS mutation or an electron transport chain defect depended on glutamate oxaloacetate transaminase 1 (GOT1) to support cell proliferation." (PMID 29751795, 2018). "Aberrantly mutated KRAS has been shown to play a critical role in cancer initiation and maintenance by modulating oncogenic downstream effectors including Raf and PI3K, followed by the Raf/MEK/ERK and the PI3K/Akt pathways, respectively." (PMID 29504894, 2018). "The associations of KRAS mutation with peritoneal dissemination or cancer metastases have been extensively studied." (PMID 30509235, 2018). "The most frequently mutated RAS subfamily genes in cancer are KRAS, NRAS, and HRAS, which serve as intercellular signaling molecules to transduce extracellular signaling from receptor tyrosine kinase to downstream effectors." (PMID 28748451, 2018). "We also analyzed the functional effects of combined dabrafenib and trametinib in other lung (n = 5) and pancreatic (n = 6) cancer cell lines characterized for KRAS/BRAF mutational status." (PMID 29986755, 2018). "The results indicate that CRISPR-Cas9-mediated genome editing can potentially be used for the treatment of cancer patients, specifically those with oncogenic KRAS mutations." (PMID 30089886, 2018). "KRAS mutations represent an early event during pancreatic tumorigenesis that crucial for cancer initiation and progression." (PMID 30533257, 2018).
cancer (continued). "As expected, KRAS mutant-specific CRISPR/Cas9 selectively inhibited the growth of various cancer cell lines with KRAS mutations in vitro." (PMID 30089886, 2018). "We included this penalty because our model is based on empirical data of a KRAS mutant cancer cell line (A549 cell), where the resulting KRAS protein is constitutively active." (PMID 29522507, 2018). "This study has provided evidence that KRAS exon 2 mutations are concentrated in CD166-positive cancer cells, with prognostic significance in CRC, and those mutations are also detected in CAD." (PMID 29755662, 2018). "KRAS mutation, one of the most common molecular alterations observed in adult carcinomas, was reported to activate the anti-oxidant program driven by the transcription factor NRF2 (Nuclear factor-erythroid 2-related factor 2)." (PMID 29507676, 2018). "The GeneReader NGS system offers an effective and efficient method to identify somatic (KRAS) cancer mutations." (PMID 28532404, 2017). "Down regulation of TLR3 in the CRC cell line HCT116 which constitutively harbors KRAS mutation improves the anti-cancer activity of the reovirus." (PMID 28422714, 2017). "Mutations activating KRAS underlie many forms of cancer, but are refractory to therapeutic targeting." (PMID 28807782, 2017). "The mutation that we detected in codon 12 of KRAS (G12D) is a common and important driver in pancreatic and other cancers and is concordant with that found by whole genome sequencing of these same samples." (PMID 28611298, 2017). "Another remarkable finding was the distinctive low expressions of miR-342-3p and let-7e in ALK-rearranged cancer, compared to EGFR/KRAS-mutated cancers." (PMID 28035073, 2017). "Given that the cancer samples are heterogeneous, a useful assay for the detection of KRAS mutations should be able to accurately detect the mutations in mixed cells with wild-type populations." (PMID 29137388, 2017). "Results obtained from such studies will have significant clinical relevance given that KRAS is the gene most frequently mutated across many cancer types." (PMID 29137294, 2017). "Activating mutations in codon 12 and codon 13 of the KRAS (Kirsten rat sarcoma viral oncogene homolog) gene are implicated in the development of several human cancer types and influence their clinical evaluation, treatment and prognosis." (PMID 28636636, 2017). "The spatio-temporal patterns of expression highlight neglected areas of Ras biology and inform models that try to explain the essential role of KRas in development and the preponderance of KRas mutations in cancer." (PMID 28117393, 2017). "The meta-analysis was performed to investigate the prognostic value of KRAS mutation detected by cfDNA on survival in cancer patients." (PMID 28796802, 2017). "The KRAS mutation is an essential step which is thought to contribute to cancer development by driving proliferation of cells and resisting to apoptosis with initiated mutations." (PMID 28328959, 2017). "A recent study investigated the differential efficacy of MEK inhibitors in KRAS-mutated cancer cells in which ERK pathway activation is supposed to be CRAF-mediated." (PMID 28947956, 2017). "Oncogenic RAS mutants are key anti-cancer targets as KRas mutations are very frequent in human cancers." (PMID 28489072, 2017). "Short-term use of the BEZ/GSK/TSA drug combination (hereafter referred to as BGT) caused growth inhibition and cell death of up to 90% of KRAS mutant cancer cells." (PMID 28152508, 2017). "RAS genes (HRAS, NRAS and KRAS) are the most frequently mutated oncogene family in human cancers, and is strongly associated with cigarette smoking." (PMID 29137294, 2017).
cancer (continued). "Several known cancer mutations were seen in unique samples (KRAS p.G12D, BRAF p.D594G, NF1 p.R1362*, and ZFAND1 p.R130*)." (PMID 28852190, 2017). "The expression patterns assist interpretation of the essential role of KRas in development and the preponderance of KRas mutations in cancer." (PMID 28117393, 2017). "BRAF testing was mostly performed directly by molecular cancer genetic platform in patients with KRAS wild-type CRC since the two mutations are mutually exclusive." (PMID 29137623, 2017). "A growing number of studies indicated that KRAS mutation was a prognostic biomarker to predict the survival outcomes in cancer patients." (PMID 28796802, 2017). "Due to this, mutations, which cause constitutive activation of KRAS, lead to uncontrolled proliferation and other processes causing cancer development and spreading." (PMID 28452926, 2017). "Our results indicate that pleural homed cancer cells harboring activating KRAS mutations are competent of MPE induction." (PMID 28508873, 2017). "A clinical benefit of the FDA-approved MEK inhibitor trametinib has been partially demonstrated in cancers with a KRAS mutation." (PMID 29089060, 2017). "Introduction of a preamplification step improved the analytic potential of the highly specific ddPCR‐based assay, establishing a reliable framework for digital quantification of oncogenic KRAS variants and other driver mutations for cancer screening." (PMID 28691390, 2017). "Our findings clearly show that the dampening of TLR3 expression makes KRAS mutated cancer cells a better therapeutic target for oncolytic reovirus." (PMID 28422714, 2017). "A remarkable application of electrochemical biosensing to cancer diagnosis has been obtained by developing a voltammetric clamp assay for the screening of KRAS mutations in ctDNA from serum samples of cancer patients." (PMID 29137122, 2017). "In contrast, low levels of DNA hypermethylation (CIMP-Low) were associated with left-sided cancers, a male predominance, KRAS mutation, BRAF wild type and MSS." (PMID 28097409, 2017). "Cancer cells that harbour mutations in the KRAS gene are expected to be highly dependent on KRAS expression compared to KRAS wild-type lines." (PMID 28972570, 2017). "Any mutation in the KRAS oncogene that causes the altered expression of translated protein can cause cancer formation." (PMID 28900470, 2017). "Several studies found that cfDNA and the presence of mutant KRAS in plasma or serum cfDNA was significantly associated with the metastasis in patients with cancer." (PMID 28796802, 2017). "KRAS (Kirsten rat sarcoma viral oncogene homolog) is a protooncogene, whose constitutive activation through point mutations drives the neoplastic transformation in many cancers." (PMID 28415695, 2017). "With the prevalence rates of 49.5%, the mutations in the KRAS gene are the most common among the RAS mutations in cancer." (PMID 28398227, 2017). "In cancers with KRAS mutations, CRAF plays a pivotal role in ERK signaling and in the early stages of oncogenesis." (PMID 28947956, 2017). "KRAS mutation detected by cfDNA was a significant prognostic biomarker in cancer patients either in Asian (HR 1.81, 95% CI 1.29–2.53, P<0.01) or others population (HR 2.21, 95% CI 1.63–2.51, P<0.01)." (PMID 28796802, 2017).
cancer (continued). "Among RAS genes, KRAS is the most frequently mutated gene in cancer (85% of RAS-driven cancers), while HRAS is the least frequently mutated gene (3%) (COSMIC)." (PMID 28152508, 2017). "We show that cancer cells bearing different KRAS mutations cause MPE upon pleural dissemination and that mutant KRAS is important for experimental MPE development." (PMID 28508873, 2017). "The KRAS gene is mutated in several cancers, including adenocarcinomas occurring in the pancreas, lung, ovary and thyroid." (PMID 28636636, 2017). "As previously alluded to, the presence of GLUT1 receptors on BRAF and KRAS mutated cells promotes this prooxidant effect of vitamin C in cancer cells." (PMID 28791253, 2017). "KRAS is mutated in more than 20% of human cancers, mostly in pancreatic (more than 90%), colorectal and lung cancers as well as leukemias." (PMID 28452926, 2017). "The published literature shows that the frequency of KRAS mutations in GBC ranges from 8% to 80% which indicates the heterogenic nature of cancer." (PMID 28900470, 2017). "Significant evidence suggests that mutation of KRAS causes constitutive activation and persistent stimulation of downstream signaling pathways, and this phenomenon can be found in many types of cancer." (PMID 27901498, 2017). "We recently showed that TRAIL signaling via TRAIL-R2 promotes invasion and metastasis of KRAS-mutated cancers by activating Rac1/phosphatidylinositol 3-kinase (PI3K) signaling." (PMID 28212753, 2017). "Compound 0375-0604 showed a strong anti-cancer activity by inhibiting the activation of KRAS proteins, and caused G2/M cell cycle arrest at the early stage and induced apoptosis at the later stage in H2122, H358 and H460 cell lines harboring KRAS oncogene." (PMID 29184501, 2017). "Literature searches of Cochrane Library, EMBASE, PubMed and Web of Science were performed to identify studies related to KRAS mutation detected by cfDNA and survival in cancer patients." (PMID 28796802, 2017). "Although our current analysis was performed only in pancreas EUS-FNAs focusing on alterations in the KRAS gene, mutations in other cancer-related genes should be readily detectable utilizing a dPCR platform." (PMID 28125707, 2017). "Some single nucleotide polymorphisms (SNPs) residing in 3′ UTRs of KRAS gene have been found effected cancer risk through altering the activation of KRAS gene." (PMID 28099923, 2017). "Our analysis showed that KRAS mutation detected by cfDNA was associated with a poorer survival in cancer patients for OS and PFS (HR = 2.02, 95% CI 1.63–2.51, P<0.01 and HR = 1.64, 95% CI 1.27–2.13, P<0.01, respectively)." (PMID 28796802, 2017). "Mutations activating the small GTP-binding protein KRAS, which occur frequently in human cancers, have proven largely refractory to therapeutic targeting." (PMID 28807782, 2017). "Ion Torrent technology (Ampliseq cancer panel) performed better than GS-454 (5 amplicons covering KRAS/EGFR hot spot) which failed in identifying KRAS mutations in four samples." (PMID 29221448, 2017). "KRAS is a central node in signaling pathways that promote cell growth and survival, and is constitutively activated by mutations in one third of cancers." (PMID 28032595, 2017). "In this study, we focused on the amino acid transporter which was exclusively regulated by mutated KRAS, although several amino acid transporters have been reported to be up-regulated in cancer." (PMID 28749408, 2017). "KRAS is the most commonly mutated oncogene, frequently associated with some of the deadliest forms of cancer." (PMID 28152508, 2017).